ITGA6 (integrin subunit alpha 6)
Diseases named in the same sentence as ITGA6 in open-access papers (continued):
Sharing a sentence is not in itself a finding about the gene and the disease.
cholangiocarcinoma (2 papers, 2018 to 2021). A carcinoma that arises from the intrahepatic biliary tree (intrahepatic cholangiocarcinoma) or from the junction, or adjacent to the junction, of the right and left hepatic ducts (hilar cholangiocarcinoma). "Moreover, expressions of six TF genes (SP1, CREB1, MAX, FHL2, RFX1, and HIF1A) was positively correlated with the expression of ITGA6 and ITGB1 in cholangiocarcinoma tissues." (PMID 34199886, 2021). "For example, cholangiocarcinoma (CHOL) overexpresses a large variety of subunits (e.g. ITGAV, ITGA1, ITGA4, ITGA5, ITGA11, ITGB1, ITGB2, ITGB6), whereas, the equally deadly pancreatic adenocarcinoma (PAAD) overexpresses a very limited set of integrins, including ITGA6 and ITGB4." (PMID 30046394, 2018).
colitis (2 papers, 2022). Inflammation of the colon. "We found that the expression of ITGA6 (integrin α6) and ITGB1 (integrin β1), which bind to TK peptides (CT), was significantly increased in the colon of mice with acute colitis." (PMID 36552583, 2022).
dilated cardiomyopathy (2 papers, 2020 to 2023). Cardiomyopathy which is characterized by dilation and contractile dysfunction of the left and right ventricles. "Dilated cardiomyopathy (DCM) pathway, including Lama2, Tnnt2, Actg1, Atp2a2, Gnas, Tpm3, Itga6, Tpm1, and Pln, was enriched in the KEGG pathway." (PMID 37858115, 2023).
Hirschsprung disease (2 papers, 2021 to 2025). Hirschsprung disease (HSCR) is a congenital intestinal motility disorder that is characterized by signs of intestinal obstruction due to the presence of an aganglionic segment of variable extent in the terminal part of the colon. "Of these genes, LAMA4, ZEB2, CTNNAL1, ITGA6 and ITIH5 have previously been associated with Hirschsprung’s disease and ZEB2 was shown to genetically interact with SOX10." (PMID 39982575, 2025).
infertile (2 papers, 2018 to 2023). "Spermatogenesis was reconstituted in infertile male mice after colonization assays in recipient testes using testis cells expressing ITGA6." (PMID 36742450, 2023). "Following transplantation into infertile mouse testes, donor SSCs reconstituted spermatogenic colonies in the recipient testes, and in previous studies, approximately 200 spermatogenic colonies per 105 THY1lo ITGA6+ spermatogonia transplanted were generated." (PMID 29769589, 2018). "Moreover, ITGA6 downregulation and upregulation of alpha 1 and alpha 2 chains of type VI collagen in the testis suggest that alterations of PI3K/AKT and FA pathways might represent the molecular mechanism behind the estrogen/cold-induced infertility." (PMID 36742450, 2023).
laryngeal squamous cell carcinoma (2 papers, 2022 to 2025). A squamous cell carcinoma that arises from the larynx. "They used a real-time quantitative fluorescence PCR (RT-qPCR) to analyze the mRNA expressions of MAPK10, c-Jun, and Itga6 genes in the pretreatment samples of 57 laryngeal squamous cell carcinoma patients." (PMID 35875133, 2022).
latent infection (2 papers, 2010 to 2024). "Laminin receptor ITGA6 is down-regulated during latent infection but up-regulated during recurrent infection." (PMID 21067549, 2010).
liver disease (2 papers, 2023). "Upon examination of the expression of ITGA6 in the multistage liver disease dataset GSE114564, a significant increase in expression was noted, and AUC analysis also confirmed the superior performance of ITGA6 as an HCC diagnostic factor." (PMID 37627184, 2023). "Similar results were observed in another multistage liver disease dataset, GSE6764, further validating the increase in ITGA6 expression with advanced HCC stages and its remarkable diagnostic ability for HCC." (PMID 37627184, 2023).
lung diseases (2 papers, 2022 to 2024). "Based on pathway enrichment analysis, genes altered in BPD blood cells were mainly enriched in cell cycle regulation and arrest (e.g., PPP2CA, RBL2, CENPU, CCNY, CDK6) and pulmonary disorder and developmental disorders (e.g., AGER, ITGA6, CA4, BACH2, IGFBP2, BMPR2, SKI, DAB2)." (PMID 35484630, 2022).
lymph node metastases (2 papers, 2022). "Importantly, high PLEC levels and lymph node metastasis, Gleason score, PSA level, and metastasis all were positively correlated in double stratified ITGB4 or ITGA6 low, and PTEN low or PTEN copy loss number patients’ groups." (PMID 35773413, 2022). "Furthermore, the patients with lymph node metastases (N >0) and high TNM stage (III and IV) showed a lower expression of MAPK10 and an overexpression of Itga6." (PMID 35875133, 2022).
oral squamous cell carcinoma (2 papers, 2024 to 2025). "For instance, miR-186-5p inhibits oral squamous cell carcinoma progression by targeting the integrin subunit alpha 6 (ITGA6) gene, thus affecting the phosphoinositide 3-kinase (PI3K)/AKT signaling pathway." (PMID 41226766, 2025). "Forced ITGA6 expression elevates PI3K and Akt phosphorylation levels in oral squamous cell carcinoma cells, but its inhibition impairs the activity of the PI3K/Akt pathway." (PMID 38493128, 2024).
osteoporosis (2 papers, 2020 to 2021). A condition of reduced bone mass, with decreased cortical thickness and a decrease in the number and size of the trabeculae of cancellous bone (but normal chemical composition), resulting in increased fracture incidence. "In addition, the study of these molecules SNTG2, TRAF3IP2, and ITGA6 can be tested as therapeutic targets in osteoporosis‐related VF." (PMID 32602654, 2020). "XPR1, SLC4A2, and GNPTAB were previously reported to be related to osteoporosis, but GRAMD1B, ITGA6, and DUSP6 have never been studied with respect to any musculoskeletal-related diseases." (PMID 34475393, 2021).
type 2 diabetes (2 papers, 2014 to 2023). "SNPs near Pdk1 and Itga6 are potentially associated with many metabolic phenotypes in the human population, such as BMI, fasting glucose, type 2 diabetes, total cholesterol, and triglycerides." (PMID 36717164, 2023). "Moreover, not only rare variant SNPs (in the Gpr155) but also common variants (in the Itga6, Zak, and Mtx2) could be candidate genes for type 2 diabetes caused by the gene-gene interaction." (PMID 24789282, 2014).
aortic aneurysm (1 paper, 2025). A ruptured aneurysm located in the wall of the proximal portion of the descending aorta proceeding from the arch of the aorta. "Taken together, these results suggest that HINT1 in VSMC aggravates aortic aneurysm by increasing the expression of ITGA6." (PMID 40198125, 2025). "Knockout of Hint1 in VSMCs alleviated aortic aneurysm, and simultaneous overexpression of Itga6 reversed this protective effect." (PMID 40198125, 2025). "We found increased ITGA6 in aorta samples from aortic aneurysm patients than that in normal aorta samples from donors by Western blot and q-PCR." (PMID 40198125, 2025). "Defactinib, an inhibitor of FAK, significantly limited aortic aneurysm progression in mice by targeting the ITGA6/FAK axis." (PMID 40198125, 2025). "Taken together, these results indicate that ITGA6 in VSMCs causes VSMC phenotypic switching and aggravates aortic aneurysms in vivo." (PMID 40198125, 2025). "HINT1 promotes VSMC phenotypic switching and aortic aneurysm by targeting ITGA6/FAK axis." (PMID 40198125, 2025). "Silencing Itga6 resulted in decreased incidence of aortic aneurysm and reduced aortic diameter." (PMID 40198125, 2025). "Impact of HINT1 on aortic aneurysm relies on its regulation of ITGA6." (PMID 40198125, 2025). "To clarify the role of ITGA6 in aortic aneurysm, we injected lentivirus vector encoding negative shRNA control (Lenti-shNC) or lentivirus vector encoding shRNA targeting Itga6 (Lenti-shItga6) with 2 reverse loxP sites, which can be recognized by Cre recombinase." (PMID 40198125, 2025). "Thus, the HINT1/ITGA6/FAK axis emerges as a potential therapeutic strategy in aortic aneurysm." (PMID 40198125, 2025). "Taken together, these findings demonstrated that HINT1 promotes VSMC phenotypic switching and aggravates aortic aneurysm in an ITGA6-dependent manner through direct interaction with TFAP2A, which is responsible for the transcriptional activation of ITGA6." (PMID 40198125, 2025). "However, the role of ITGA6 in VSMC phenotypic switching or aortic aneurysms has not been elucidated." (PMID 40198125, 2025).
aplasia cutis congenita (1 paper, 2023). Aplasia cutis congenita (ACC) is a rare skin disorder characterized by localized absence of skin that is usually located on the scalp but can occur anywhere on the body including the face, trunk and extremities. "We present a case of lethal JEB and pyloric atresia with aplasia cutis congenita (ACC), with a homozygous pathogenic variant identified in the ITGA6 gene, c.1688dup." (PMID 37525771, 2023).
autism spectrum disorder (1 paper, 2025). A spectrum of developmental disorders that includes autism, and Asperger syndrome. "In this study, through the analysis of CHD8A and CHD8B allelic deletion samples, we identified seven hub genes associated with Autism Spectrum Disorder (ASD): IGF2, FN1, CXCR4, COL11A1, ITGA6, LOX, and FBN2." (PMID 40526590, 2025).
brain cancer (1 paper, 2019). A primary or metastatic malignant neoplasm affecting the brain. "Additionally, our studies suggest that the ALDHbright population validates the CSC phenotype based on the increased expression of brain cancer stem cells genes such as ALDH1A1, ITGA6, THY1, PROM1, and SOX2." (PMID 30646520, 2019).
CNS leukemia (1 paper, 2023). "Because CNS leukemia is mediated by ITGA6–laminin interactions, ITGA6 might be a viable target for more sensitive and noninvasive diagnostic approaches to targeted molecular CNS leukemia imaging." (PMID 37444576, 2023).
cutaneous squamous cell carcinoma (1 paper, 2023). "(J) Immunohistochemistry staining of MAGEA4 and ITGA6 in human skin of normal, SCCIS, and cutaneous squamous cell carcinoma (cSCC) samples." (PMID 38099574, 2023).
enamel hypoplasia (1 paper, 2023). "Individuals with EB caused by mutations in laminin-332 (Lama3, Lamb3, Lamc2), α6ß4-integrin (TGB4, ITGA6) gene and type XVII collagen (Col17A1) are associated with enamel hypoplasia." (PMID 37511997, 2023).
ependymoma (1 paper, 2023). A WHO grade II, slow growing tumor of children and young adults, usually located intraventricularly. "Fluorescence activated cell sorting (FACS) shows that the slight but significant increase of ITGA6 transcription translates to high ITGA6 protein abundance specifically in PFA compared with ZFTA ependymomas and normal human fetal neuronal stem cells (HF7450)." (PMID 37085539, 2023). "Based on these results, we hypothesized that ITGA6 is essential for the proliferation of PFA ependymoma in a disease sub-group specific manner." (PMID 37085539, 2023).
epilepsy (1 paper, 2024). A brain disorder characterized by episodes of abnormally increased neuronal discharge resulting in transient episodes of sensory or motor neurological dysfunction, or psychic dysfunction. "CSNK2B is also connected to cell signaling pathways, alongside ITGA6 and Furin, with documented contributions to neurodevelopmental disorders, epilepsy, and the classical GBM subtypes." (PMID 39123468, 2024).
esophageal cancer (1 paper, 2017). A primary or metastatic malignant neoplasm involving the esophagus. "Additionally, knockdown of ECT2 and ITGA6 expression suppressed esophageal cancer cell growth and proliferation." (PMID 29108269, 2017).
esophageal squamous cell carcinoma (1 paper, 2016). Esophageal squamous cell carcinoma (ESCC) is a type of esophageal carcinoma (EC) that can affect any part of the esophagus, but is usually located in the upper or middle third. "Additionally, in esophageal squamous cell carcinoma (ESCC), ITGA6 was found to be highly expressed." (PMID 27502506, 2016).
gastric tumors (1 paper, 2013). "Consistent with this, we found that SOX2, POU5F1 (a gene encoding OCT4) and ITGA6 were all strongly expressed in human gastric tumors examined, except that SOX2 was not expressed by MKN74 cell line." (PMID 24015244, 2013).
glaucoma (1 paper, 2025). Increased pressure in the eyeball due to obstruction of the outflow of aqueous humor. "Correspondingly, transplantation of an ITGA6-enriched preparation of iPSC-TM into the eyes of animal models of glaucoma had a much stronger effect on tissue regeneration, including IOP reduction and increased aqueous humor outflow facility, than those with low ITGA6+ cellularity." (PMID 41145463, 2025).
human papillomavirus infection (1 paper, 2024). "The upregulated genes (n = 135) included ATM, COL1A1, FN1, ITGA6, and LAMB1, which were found to be enriched in pathways related to human papillomavirus infection and herpes simplex virus 1 infection." (PMID 40226717, 2024).
infarction (1 paper, 2023). A localised pathological necrosis of tissue resulting from obstruction of the blood supply usually by a thrombus, an embolus, or vascular torsion. "Infarct macrophages exhibited marked induction of Itga5, Itgav and Itga6 that was first noted 3 days after infarction and further increased at the 7-day timepoint." (PMID 37985764, 2023).
invasive carcinoma (1 paper, 2021). A carcinoma that is not confined to the epithelium, and has spread to the surrounding stroma. "ITGB4, a member of the integrin family, mediates cell-cell adhesion or cell growth and plays a significant role in the biology of invasive carcinoma by associating with integrin alpha 6 (ITGA6) subunit." (PMID 34745421, 2021).
lung hypoplasia (1 paper, 2013). "The present work also suggests the involvement of ITGA6 deficiency in CDH, as TO restored ITGA6 mRNA levels concomitantly with the correction of lung hypoplasia." (PMID 23840910, 2013).
mesothelioma (1 paper, 2021). A usually malignant and aggressive neoplasm of the mesothelium which is often associated with exposure to asbestos. "We then expanded the gene panel to include ITGA6, PD-L1, and MMP1, which were previously shown to be upregulated by EGF in EMT models of mesothelioma." (PMID 33777943, 2021).
multiple myeloma (1 paper, 2023). "Elevated levels of ITGA6 inhibit myeloma cell invasion, whereas decreased ITGA6 expression promotes myeloma metastasis." (PMID 37444576, 2023). "Furthermore, ITGA6 is considered a good predictive marker in several cancers, such as stomach adenocarcinoma and multiple myeloma." (PMID 37444576, 2023).
muscular dystrophy (1 paper, 2016). Muscular dystrophy (MD) refers to a group of more than 30 genetic diseases characterized by progressive weakness and degeneration of the skeletal muscles that control movement. "Notably, the expression of ITGA5 and ITGA6 has been linked to active regeneration of skeletal muscle in muscular dystrophy, and both of these integrins were expressed only in the mutant samples (with the intensity for both components being between 1 × 106 and 1 × 108)." (PMID 27099343, 2016).
Nail dystrophy (1 paper, 2024). Onychodystrophy (nail dystrophy) refers to nail changes apart from changes of the color (nail dyschromia) and involves partial or complete disruption of the various keratinous layers of the nail plate. "The nail dystrophy observed in this girl expands the clinical spectrum of skin and connective tissue manifestations associated with biallelic mutations in ITGA6." (PMID 39583125, 2024). "Since the whole-exome sequencing is otherwise negative, and the family history does not suggest any other skin disorder, the likelihood of coincidentally finding biallelic ITGA6 mutations in a child with congenital pyloric atresia and nail dystrophy, seems extremely low." (PMID 39583125, 2024).
nasopharyngeal carcinoma (1 paper, 2025). A carcinoma arising from the nasopharyngeal epithelium. "Notably, NAT10 extends its regulatory reach beyond protein-coding RNAs—ac4C modification of lncRNA SIMALR enhances its stability, enabling activation of eEF1 A2-mediated ITGB4/ITGA6 translation in nasopharyngeal carcinoma." (PMID 40588654, 2025).
oral cancer (1 paper, 2023). "ITGA6 can also promote cell invasion by changing the microenvironment of the extracellular matrix (ECM), suggesting a new way for oral cancer treatment by silencing the molecule." (PMID 37555363, 2023).
papillary thyroid carcinoma (1 paper, 2021). "In their study, ITGA6 was validated as a target of miR-363-3p, suggesting that metastatic cascade of papillary thyroid carcinoma is partly regulated by the miR-363-3p/ITGA6 axis." (PMID 33435156, 2021).
plasma cell leukemia (1 paper, 2024). An aggressive plasma cell neoplasm characterized by the presence of neoplastic plasma cells in the peripheral blood. "Importantly, we detected lower expression of CXCR4, which encodes a key molecule for PCs homing to the BM, and integrin gene ITGA6, the downregulation of which was recently connected to progression from MM to plasma cell leukemia." (PMID 38493239, 2024).
rheumatoid arthritis (1 paper, 2024). A chronic, systemic autoimmune disorder characterized by inflammation in the synovial membranes and articular surfaces. "KEGG pathway analysis of the upregulated proteins in ENTPD1+CD55+ cells indicated enrichment for proteins involved in rheumatoid arthritis (e.g., HLA-DRA, ICAM1) and ECM–receptor interaction (e.g., type I collagen, Laminin subunit alpha-5, integrin-subunit alpha-6)." (PMID 38612896, 2024).
salivary gland adenoid cystic carcinoma (1 paper, 2025). An adenoid cystic carcinoma arising from the salivary gland. "In salivary gland adenoid cystic carcinoma, increased ADAMTS9-AS2 expression lowers ITGA6 levels via miR-143-3p, indirectly affecting both the PI3K/Akt and MEK/Erk pathways." (PMID 40350996, 2025).
skin inflammation (1 paper, 2020). "For this we undertook a whole transcriptome analysis of basal CD49f+ (Itga6) keratinocytes of Sox13-/- mice at 3 and 7 weeks (wks), well before the onset of aberrant skin inflammation starting in ~3 months old (mo) mice." (PMID 32065580, 2020).
Stroke (1 paper, 2021). Sudden impairment of blood flow to a part of the brain due to occlusion or rupture of an artery to the brain. "ITGA6 has a potentially versatile role in the cardiovascular system due to containing intron SNPs that correlate with VLDL, echocardiography, platelet function tests, and stroke." (PMID 33860000, 2021).
thrombosis (1 paper, 2019).
thyroid cancer (1 paper, 2012). "The expression of the ITGA6/ITGB4 complex could promote tumor progression and the metastasis of various cancer cells, including breast, colorectal, and thyroid carcinomas." (PMID 22295105, 2012).
Vestibular schwannoma (1 paper, 2025). A vestibular schwannoma (also known as acoustic neuroma, acoustic neurinoma, or acoustic neurilemoma) is a benign, usually slow-growing tumor that develops from the VIIIth cranial nerve supplying the inner ear. "Our cell communication analysis based on the curated receptor-ligand pair database showed that fibroblast in vestibular schwannoma microenvironment mainly regulated the biological behavior of tumor cells through PSAP/GPR37L1, MDK/(ITGA6 + ITGB1), IGF2/(ITGA6 + ) and MDK/LRP1 signaling axes." (PMID 40629113, 2025).
viral infection (1 paper, 2022). "Therefore, ITGA6 is involved in the immune cell infiltration of the lung upon viral infection." (PMID 35928229, 2022).